KLRG1 (killer cell lectin like receptor G1)
Diseases named in the same sentence as KLRG1 in open-access papers (continued):
Sharing a sentence is not in itself a finding about the gene and the disease.
tumor (continued). "Regarding tumor development, enrichment of KLRG1+ T cells and NK cells in the tumor microenvironment has been observed in human tumors." (PMID 35572605, 2022). "KLRG1+ NK cells play a role in the control of tumor growth, particularly in controlling metastasis formation." (PMID 33467442, 2021). "Α 4-1BB caused a significant up-regulation of killer cell lectin-like receptor G1 (KLRG1) on CD8+, and less extent the up-regulation of effector T-cells and CD4+ in the tumor." (PMID 34267616, 2021). "Further, in studies of KLRG1+ iNKT cell induction by antigen-loaded DCs, these cells maintain long-term anti-tumor function." (PMID 33664261, 2021). "The results showed that knockdown of KLRG1 enhanced the proliferation of A549 and H1299 tumor cells." (PMID 34187403, 2021). "There is only one paper published in Oncotarget which investigated the expression of KLRG1 on tumor cells." (PMID 34187403, 2021). "Multi-parametric immunofluorescence analyses indicated that CD8+ TIL from anti-PD-1-treated B16F10E-KO tumours was more enriched with terminally differentiated KLRG1+ effector T cells than those from isotype-treated B16F10E-KO and anti-PD-1-treated B16F10E." (PMID 34471106, 2021). "To further investigate the interaction of the four factors, we analyzed the expression levels of BTK, CCR2 and SCLM4 in KLRG1 knockdown A549 tumor cells." (PMID 34187403, 2021). "We also established stable LUAD cell lines with KLRG1 gene knockdown and investigated the effect of KLRG1 knockdown on tumor cell proliferation." (PMID 34187403, 2021). "The role of KLRG1 has been associated with an exhausted phenotype; however, mature NK cells expressing KLRG1 are more efficient in the eradication of some tumor types." (PMID 33621210, 2021). "The same authors showed that anti-KLRG1 antibody monotherapy in a 4T1 breast cancer mouse model enhanced tumor control compared to controls." (PMID 34025641, 2021). "And a lower expression levels of KLRG1, BTK, CCR2, SCML4 were all associated with advanced neoplasm disease stage." (PMID 34187403, 2021). "How KLRG1 influences tumor cells proliferation is an interesting question which deserves further study." (PMID 34187403, 2021). "PD-1/PD-L1 and CD8 T cells are closely related, as PD-1 blockade can increase CD8 T cell and tumor-specific interferon-γ production in the tumor microenvironment or produce anti-tumor effects by increasing KLRG1 + LAG3 - TNFα+ tumor-specific T cells in tumors." (PMID 34439378, 2021). "Expression of maturation markers like CD27, CD11b and KLRG1 (Killer cell Lectin-like Receptor G1), separate individual NK cell subpopulations based on responsiveness, migratory capacity and anti-tumour activity." (PMID 34516566, 2021). "Recently, a new role for KLRG1 has emerged as an inhibitory receptor impacting NK cell function in tumor surveillance." (PMID 34025641, 2021). "The decreased level of E-cadherin in the tumor microenvironment will reduce the inhibitory role of KLRG1 on T cells and NK cells, which leads to high release of degranulation and interferon γ." (PMID 34187403, 2021). "In that study, it showed that KLRG1 expression is upregulated in human tumor samples after a variety of therapies, including radiation, endocrine therapy, chemotherapy, and immunotherapy." (PMID 34187403, 2021). "Compared to wild-type animals, Tregs from stage 1 show reduced expression of Klrg1 and Il1rl1, two markers of tissue resident Tregs, suggesting an early influx of Tregs from the circulatory system preceding tumour formation." (PMID 33686070, 2021). "VISTA, TIGIT and KLRG1 showed a trend towards increased expression in patients with high grades of tumor budding." (PMID 32393998, 2020). "Beyond PD-1, a combination of anti-TIGIT or anti-KLRG1 antibodies and DNA methyltransferase inhibitor reversed the metastasis-promoting state acquired by certain tumor-exposed NK cells." (PMID 33120910, 2020).
tumor (continued). "Another co-inhibitory receptor, KLRG1, expressed on late-differentiated effector cells and CD8+ T and NK cells, is up-regulated in treated tumor samples, resulting in drug resistance; blocking both KLRG1 and PD-1 can improve outcomes." (PMID 32000802, 2020). "Recently, a new role for KLRG1 has emerged as an inhibitory receptor in the context of tumor control." (PMID 32290478, 2020). "We found that mRNA levels of PD-1, TIM-3, CTLA-4, TIGIT, CD160, CD244, and KLRG1 were elevated in CRC tumor tissue, implicating their potential contribution to CRC development and/or progression." (PMID 32393998, 2020). "In cancer, NK cell senescence has not been clearly defined, but NK cells do release SASP-like molecules in response to tumor cells, and upregulate KLRG1 and ATM phosphorylation, key senescence markers, in response to chronic stimulation." (PMID 33120910, 2020). "In human blood and tumor samples, KLRG1 expression is aligned with cytotoxic T and NK cell differentiation, and upregulated in human tumor samples after a variety of therapies, potentially contributing to adaptive resistance." (PMID 30858925, 2019). "These tumor-associated ILC1s express higher levels of inhibitory receptors (NKG2A, KLRG1, CTLA4, LAG3) as compared to NK cells." (PMID 31105707, 2019). "Immunofluorescent staining in B16 lung metastatic also showed that more KLRG1+CD8 T cells (yellow) infiltration into tumor sites in DBA DC-vaccinated mice." (PMID 31664180, 2019). "We wondered if adequate activation of KLRG1+CD8 T cells in these mice was effectively triggered in mice with higher tumor burden." (PMID 31664180, 2019). "Tumour‐associated Treg cells are known to express numerous co‐stimulatory (i.e. ICOS, OX40, GITR) and co‐inhibitory (i.e. Lag‐3, Klrg1, Tim‐3, TIGIT, PD‐1) receptors that modulate their function." (PMID 31032905, 2019). "Specifically, the late-differentiated CMV-specific T effector like phenotype (CD57-high, KLRG-1-high and 2B4-high) also seen in the majority of the neoantigen-specific T cells from atezolizumab responders may be associated with senescent cells with highly cytotoxic and strong anti-tumor activity." (PMID 31511069, 2019). "Quantification of tumor numbers per lung revealed that KLRG1+ NK cells from Ackr2−/− mice were significantly better at suppressing tumor development than WT counterparts (Fig. 7Fiii)." (PMID 30158126, 2018). "Accordingly, we identified CXCR3+KLRG1− T cells in tumor-draining lymph nodes, that were capable of seeding tumor-specific Trm responses in the skin following i.v. adoptive transfer." (PMID 30555481, 2018). "KLRG-1 on terminal effector T cells has been shown to be involved in effective anti-tumour reactions." (PMID 28916749, 2017). "Next we assessed the contribution of the KLRG1+CD8+ population at facilitating tumor rejection induced by the triple combination therapy by depleting KLRG1+CD8+ cells in tumor-bearing mice." (PMID 28388572, 2017). "Natural killer (NK) cells are known to express KLRG1, however, it is unlikely that in this model NK cells played a central role in tumor efficacy." (PMID 28388572, 2017). "In a pulmonary metastatic colorectal model, KLRG1+ NK cells were shown to be crucial in protecting against tumor development in a perforin-dependent manner." (PMID 29198913, 2017). "The numbers of tumor foci inversely correlated with KLRG1+ NK cell frequencies, therefore indicating an important role of these cells in controlling metastasis formation." (PMID 26822794, 2016). "The analysis of WASp KO NK cells implies that increased expression of KLRG1, LAG-3 and DNAM-1 was associated with normal tumor rejection capacity, at least when multiple ligands and cytokines such as IL-2 was produced by tumor cells." (PMID 27477778, 2016). "The results indicated that human T cells in tumor microenvironment expressed increased level of KLRG1." (PMID 27557510, 2016).
tumor (continued). "Analysis of the T-cell exhaustion markers PD-1 and KLRG1 showed that the expression of these molecules was greater on OT-1 cells in B16-OVA-shUSP18 tumor-bearing mice than B16-OVA-shCon tumor-bearing mice." (PMID 24884733, 2014). "CD8 T cells phenotyped by CD127 and KLRG-1 biomarkers showed that poxvirus-based immunotherapy potently induces peripheral and tumor-infiltrating SLECs and DPECs which are activated effector cells with cytotoxic activity." (PMID 25328681, 2014). "Tumor-specific T-cells from TILN were lower in KLRG-1 expression but higher in TIM-3, LAG-3 and CTLA-4 expression as compared to cells with the same specificity in blood." (PMID 22347406, 2012). "By examining the absolute number of infiltrating KLRG1+ T-cells, however, we found that combination therapy results in 1.7-fold more CD4+KLRG1+ effector T-cells per mm3 of tumor relative to α4-1BB alone." (PMID 21559358, 2011). "The phenotype of these KLRG1+ tumor-infiltrating T-cells and their contribution to tumor rejection is of intense interest to us and will be the focus of future study." (PMID 21559358, 2011). "This suggests either selective expansion and/or recruitment of these cells within the tumor microenvironment, or establishment of a cytokine environment capable of converting the majority of tumor infiltrating T-cells to the KLRG1+ phenotype." (PMID 21559358, 2011). "4-1BB agonist antibody treatment induced widespread expression of the molecule killer cell lectin-like receptor subfamily G member 1 (KLRG1) as well as the co-inhibitory receptor programmed death 1 (PD-1) on tumor-infiltrating CD8+ and CD4+ effector T-cells." (PMID 21559358, 2011). "We also found that although the numbers of KLRG1+ effectors per mm3 of tumor were higher with combination treatment versus α4-1BB alone, the numbers of highly-suppressive KLRG1+ Tregs were also increased." (PMID 21559358, 2011). "Anti 4-1BB treatment, with or without CTLA-4 blockade, induced approximately 75% of CD8+ and 45% of CD4+ effector T-cells in the tumor to express the killer cell lectin-like receptor G1 (KLRG1)." (PMID 21559358, 2011). "Although KLRG1 levels were lower on T cells in tumors compared with blood, a proportion of T cells maintained KLRG1 expression in tumors and can still be inhibited by tumor E-cadherin." (PMID 40299576, 2025). "Furthermore, KLRG1 is expressed on at least 80% of these tumor-shared CD4+ T cell clones in the periphery, and KLRG1+ blood populations are highly enriched for tumor-matching clones in ex vivo–expanded CD4+ T cells from paired patient blood and tumors." (PMID 40299576, 2025). "Therefore, responders are expected to exhibit lower proliferation of KLRG1 expression in these cells to maintain tumor suppression, especially after pembrolizumab treatment, as supported by our data (not shown in the figure)." (PMID 40654678, 2025). "Interestingly, in the NKim subset, expression of IL15 and inhibitory receptor KLRG1 increased significantly with tumor progression; chemokine receptor CXCR3 expression increased with tumor grade in both NKctx and NKim cells." (PMID 40821787, 2025). "We hypothesized that the activity of cytotoxic CD4+ T cells is gated by engagement of KLRG1 by E-cadherin on tumor cells via direct interaction." (PMID 40299576, 2025). "We also confirmed that the observed death from CD4+ T cell coculture was from tumors (using directly labeled tumor target cells) and not T cells, and that E-cadherin blockade can also enhance CD8+ T cell tumor killing in a KLRG1-dependent manner despite some spontaneous killing activity." (PMID 40299576, 2025). "Administration of a bromodomain inhibitor also partially depleted intratumoral Tregs, and when this treatment is combined with anti-KLRG1 antibody, tumor-infiltrating CD8+ T-cells express higher levels of granzyme B and IFN-γ, significantly improving the antitumor response." (PMID 38898461, 2024).
tumor (continued). "Several checkpoint and inhibitory receptors, such as PD-1 (gene name: PDCD1), CTLA4, TIM-3 (HAVCR2), LAG3, CD39 (ENTPD1), CD160, KLRG1, CD96, BTLA, 2B4, and TIGIT, have been implicated in the reduction of immune activity and response in the tumor micro-environment." (PMID 39513882, 2024). "Additionally, we offer an overview of the recent advancements in KLRG1 inhibitor development for tumor immunotherapy, underscored by the promising synergistic efficacy of KLRG1 inhibitors combined with other targeted inhibitors." (PMID 38898461, 2024). "Analysis of T cells in tumor tissue revealed a significantly increased percentage of NKp46+ (p = 0.006) and FasL+ (p = 0.003) and a decreased percentage of KLRG1+ (p = 0.01), and PD-1+ (p = 0.009) of CD3+CD49− cells in the metformin-treated group compared to the control group." (PMID 38892058, 2024). "KLRG1 can inhibit the antitumor activity of immune cells and promote tumor metastasis." (PMID 38898461, 2024). "By blocking N-cadherin or disrupting its interaction with KLRG1, it may be possible to restore NK cell functionality, potentially curtailing tumor metastasis and recurrence." (PMID 39192980, 2024). "However, this antitumor effect of KLRG1 expression on tumor cells contradicts its protumor effect on immune cells." (PMID 38898461, 2024). "Therefore, in the study of the role of KLRG1 on tumor cells, KLRG1 expression levels on the surfaces of both immune cells and tumor cells should be measured." (PMID 38898461, 2024). "We speculate that the activated DC that remained in the tumor site account for the observed intra‐tumoral KLRG1+ CD8+ T‐cells." (PMID 38400597, 2024). "In patients with solid tumors, KLRG1 may affect the proliferation of tumor cells or participate in the regulation of tumor immune escape and immune tolerance by interacting with cell surface receptor signaling pathways." (PMID 38898461, 2024). "Finally, we showed the sE-cadherin/KLRG1 inhibitory receptor is the major pathway for necroptosis-mediated suppression of the anti-tumor activity of T cells and the promotion of metastasis." (PMID 36703228, 2023). "Notably, the expression level of CD69 and KLRG1 were significantly reduced in the spleen, blood and tumor of TKO animals, indicating that these cells are less activated compared to those in WT controls." (PMID 37520575, 2023). "As PLC/PRF/5 cells express E- and N- Cadherins, ligands of KLRG1, the elevated levels of KLRG1 in the effector memory cells of aging mice might have contributed to greater inhibition of anti-tumor activity." (PMID 37752597, 2023). "The data above suggest that Cxcr3 and Klrg1 may define distinct T cell differentiation states during invasive tumor growth." (PMID 36472588, 2023). "As expected, CXCR3 and KLRG1 were decreased in tumor vs. spleen." (PMID 36472588, 2023). "Finally, we showed that sE-cad/KLRG1 pathway plays a major role in mediating necroptosis-triggered inhibition of the anti-tumor activity of T cells." (PMID 36703228, 2023). "Cxcr3+ Klrg1-tetramer + T cells frequency progressively decreased in spleen and tumor over time." (PMID 36472588, 2023). "However, tumor-specific T cells infiltrating primary tumors progressively downregulate both Cxcr3 and Klrg1 while upregulating exhaustion markers PD-1 and Lag-3." (PMID 36472588, 2023). "There was a higher percentage of GZMB producing CD8+ T cells and higher expression of KLRG1 which is upregulated in highly cytotoxic effector CD8+ T cells in the tumor draining lymph node (LN) harvested from 5-NL treated mice at day 13 post tumor inoculation." (PMID 37582744, 2023). "KLRG1 expression is tied to antigen-experience and aligned with cytotoxic T and NK cell differentiation, and up-regulated in human tumor samples after a variety of therapies that resulted in T cell proliferation, potentially contributing to adaptive resistance." (PMID 37231145, 2023).
tumor (continued). "The population of PD-1- / KLRG-1- / IL-7Rα+ cells may correspond to a bystander naïve CD8 T cell population migrating to the tumor attracted by the inflammatory environment of the tumor." (PMID 37033927, 2023). "The SLECs PD1+ CD8 T cell population (KLRG-1+ / IL-7Rα-) that clonally expanded in response to the tumor was restricted to CD8 T cells co-expressing PD-1, as SLECs PD-1- CD8 T cells were almost undetectable in the tumor infiltrates of both HVEM WT and HVEM KO tumors." (PMID 37033927, 2023). "As sE-cad has been reported to be a ligand for KLRG1 and we observed significant elevation of sE-cad levels in TIF and serum of WT tumors and mice, we then investigated the possibility that necroptosis engages KLRG1 to inhibit the anti-tumor activity of T cells." (PMID 36703228, 2023). "E-cadherin-expressing target cells are well known to inhibit the cytotoxicity of tumor-activated NK cells by binding to the receptor KLRG1, but it is unclear whether virus-activated NK cells could be inhibited." (PMID 37040283, 2023). "To test this hypothesis, we quantified the percentage of each Cxcr3/Klrg1 subset that bound tetramer in KPC2a tumor-bearing mice." (PMID 36472588, 2023). "Importantly, neutralizing KLRG1 with antibody significantly elevated the anti-tumor activity of tumor-infiltrating and peripheral T cells and dramatically reduced lung metastasis in MMTV-PyMT model." (PMID 36703228, 2023). "ILC1s in tumors express high levels of the KLRG1 gene and pro-angiogenic activity and may even promote tumor progression in TGF-beta-rich tumors." (PMID 37267125, 2023). "Future studies will need to elucidate the role of KLRG1 as a potential resistance mechanism and determine whether KLRG1 can be targeted to improve anti-tumor responses in patients." (PMID 37231145, 2023). "Klrg1+ tetramer + T cell frequency progressively increased in spleen and decreased in tumor." (PMID 36472588, 2023). "Lastly, CAR T cells expressing KLRG1 mirrored the results from the in vitro cytotoxicity assay and showed markedly increased tumor burden compared to all other CAR T cells, including the CD3ζ-only CAR, while showing modest efficacy compared to untransduced T cells." (PMID 36350984, 2022). "Moreover, combination therapy increased the effector CD44+ CD8+ PD1- subset and decreased the proportion of terminally-differentiated CD103+ KLRG-1+ T-regulatory cells on both sides of tumor." (PMID 36513720, 2022). "Effector genes such as GZMB, GZMH and KLRG1 were the marker genes in clonotypes shared by all tissues, while the clonotypes present only in tumor showed upregulated T-cell exhaustion genes (HAVCR2, LAG3, CTLA4, TIGIT, PDCD1, and ICOS) and activation genes (SELL and TNFRSF9)." (PMID 36185254, 2022). "Notably, dual blockade of KLRG1 and PD-1 has been shown to decrease primary tumor growth synergistically in melanoma and CRC mouse models." (PMID 35164813, 2022). "In addition, PD-1+ tumor-infiltrating NK cells also displayed increased expression of KLRG1 compared to PD-1neg NK cells." (PMID 36185379, 2022). "Overall, we identified two tumor antigens in LUAD - KLRG1 and CBFA2T3 - that could be used to develop mRNA vaccines." (PMID 35265614, 2022). "Therefore, using KLRG1 as a tumor antigen, APCs will be trained to recognize and remove KLRG1-expressing tumor cells and senescent immune cells, becoming a new LUAD treatment strategy." (PMID 35265614, 2022). "Similarly, an abundance of KLRG1+Foxp3+CD4+ T cells appear to accrue in the tumor microenvironment of ovarian and colon cancer, suggesting their role in impaired antitumor immunity." (PMID 35572605, 2022). "Notably, the expression levels of KLRG1, BTK, CCR2, SCML4 were all associated with neoplasm disease stage (American Joint Committee on Cancer Code) (P = 0.001; P = 0.022; P = 0.004; P = 0.014, respectively)." (PMID 34187403, 2021). "The results indicated that the high expression of KLRG1 on tumor cells may induce the activation of immune cells." (PMID 34187403, 2021).